RN7SL843P (RNA, 7SL, cytoplasmic 843, pseudogene)
Gene: Miscellaneous RNA gene on chromosome 22 (17,352,881 to 17,353,177, reverse strand). Ensembl gene ENSG00000239547.
Homologues: Orthologues: chimpanzee Metazoa_SRP (98% identical), macaque Metazoa_SRP (87% identical). Paralogues in human: RN7SL126P (79% identical), RN7SL1 (77% identical), RN7SL2 (77% identical), RN7SL296P (77% identical), RN7SL3 (77% identical), RN7SL44P (77% identical), RN7SL451P (76% identical), RN7SL45P (76% identical), RN7SL14P (76% identical), RN7SL575P (76% identical), RN7SL792P (76% identical), RN7SL88P (76% identical), and 701 more.